ADAMTS12 (ADAM metallopeptidase with thrombospondin type 1 motif 12)
Description:
Metalloprotease that may play a role in the degradation of COMP. Also cleaves alpha-2 macroglobulin and aggregan. Has anti-tumorigenic properties.
Synonyms: PRO4389
Tractability: Antibody: UniProt places it where antibodies can reach, with medium confidence; UniProt predicts a signal peptide or a membrane-spanning region; its Gene Ontology location is reachable by antibodies, with medium confidence.
Target class: Enzyme; Hydrolase
Gene: Protein-coding gene on chromosome 5 (33,523,535 to 33,892,019, reverse strand). Ensembl gene ENSG00000151388.
Subcellular location: Secreted, extracellular space, extracellular matrix
Subcellular location (Human Protein Atlas): Nucleoli; Mitochondria; Predicted to be secreted
Pathways (Reactome):
Disease: Defective B3GALTL causes PpS
Metabolism of proteins: O-glycosylation of TSR domain-containing proteins
Gene Ontology:
Molecular function: metalloendopeptidase activity; protein binding; metallopeptidase activity
Biological process: cell migration; cell-matrix adhesion; cellular response to BMP stimulus; cellular response to interleukin-1; cellular response to tumor necrosis factor; negative regulation of cellular response to hepatocyte growth factor stimulus; negative regulation of cellular response to vascular endothelial growth factor stimulus; negative regulation of chondrocyte differentiation; negative regulation of hepatocyte growth factor receptor signaling pathway; protein catabolic process; proteoglycan catabolic process; regulation of endothelial tube morphogenesis; regulation of inflammatory response; extracellular matrix organization; proteolysis; chondrocyte differentiation; collagen fibril organization; ossification; ossification involved in bone maturation; proteoglycan metabolic process
Cellular component: extracellular matrix
Genetic constraint (gnomAD): Loss-of-function variants: 120 observed, 178.62 expected, observed/expected ratio (o/e) 0.67, 90% interval 0.58 to 0.78. The upper end of that interval is the gene's LOEUF score, 0.78, which puts it in group 3 of 6, group 1 being the genes least tolerant of losing a copy. Missense variants: 1,913 observed, 2,099.1 expected, observed/expected ratio (o/e) 0.91, 90% interval 0.88 to 0.95. Synonymous variants: 704 observed, 753.04 expected, observed/expected ratio (o/e) 0.93, 90% interval 0.88 to 1.
Homologues: Orthologues: macaque ADAMTS12 (96% identical), chimpanzee ADAMTS12 (94% identical), pig ADAMTS12 (85% identical), guinea pig ADAMTS12 (84% identical), rabbit ADAMTS12 (84% identical), rat Adamts12 (81% identical), mouse Adamts12 (80% identical), dog ADAMTS12 (78% identical), tropical clawed frog adamts12 (53% identical), zebrafish adamts12 (46% identical). Paralogues in human: ADAMTS7 (45% identical), ADAMTS18 (27% identical), ADAMTS9 (27% identical), ADAMTS6 (26% identical), ADAMTS16 (26% identical), ADAMTS20 (26% identical), ADAMTS10 (24% identical), ADAMTS19 (22% identical), ADAMTS17 (22% identical), ADAMTS13 (20% identical), ADAMTS3 (20% identical), ADAMTS2 (20% identical), and 13 more.
Diseases named in the same sentence as ADAMTS12 in open-access papers:
ADAMTS12 is named in the same sentence as 81 diseases in open-access papers, as found by Europe PMC text mining. Sharing a sentence is not in itself a finding about the gene and the disease. The quoted sentences say what the papers report.
breast carcinoma (13 papers, 2014 to 2025). "A protective role of ADAMTS-12 has also been found in breast cancer through its association with fibulin-2." (PMID 33996918, 2021). "First, anti-tumor properties associated to fibulin-2 in breast cancer are enhanced by its interaction with ADAMTS-12, especially in MCF-7 cells." (PMID 24457941, 2014). "Previous work in our laboratory has shown that the interaction between fibulin-2 and ADAMTS-12 promoted anti-tumor effects in breast cancer." (PMID 38396702, 2024). "In breast cancer, ADAMTS12 can suppress tumorigenesis when interacts with fibulin-2, its chaperone protein, but can also promote tumor development if fibulin-2 is absent." (PMID 37642715, 2023). "Previous studies revealed that ADAMTS12 has a great biological role in breast cancer, colorectal cancer, esophageal cancer, and other different tumors." (PMID 37642715, 2023). "ADAMTS12 is a secreted metalloprotease and plays a protumoral role in breast cancer by increasing the capacity for migration and invasion of breast cancer tumor cells." (PMID 35505821, 2022). "In breast cancer, ADAMTS-12 expression is localized preferentially surrounding the tumoral tissue and high expression is correlated with good prognosis of these patients." (PMID 33996918, 2021). "In this context, where both proteins are exogenously over-expressed, the fibulin-2/ADAMTS-12 complex not only affects the cellular properties of breast cancer cell lines but also diminishes the growth of subcutaneous tumors in mice." (PMID 31508361, 2019). "These interactions can modify the protumor properties exhibited by ADAMTS-1 and ADAMTS-12 in breast cancer cells." (PMID 31508361, 2019). "We have previously reported that ADAMTS-12 is an interacting partner of Fibulin-2 and that this interaction promotes tumor-protective effects in breast cancer cells." (PMID 28099917, 2017). "To examine the functional consequences of the ADAMTS-12/fibulin-2 interaction, we performed different in vitro assays using two breast cancer cell lines: the poorly invasive MCF-7 and the highly invasive MDA-MB-231." (PMID 24457941, 2014). "A moderate to strong expression of both fibulin-2 and ADAMTS-12 was detected in connective tissue surrounding tumor in grade 1 or 1 to 2 breast carcinoma (n=5)." (PMID 24457941, 2014). "Immunohistochemical staining revealed that ADAMTS-12 was mainly detected in the stroma of grade 1 breast carcinomas, similar to what had been previously reported in colorectal cancer." (PMID 24457941, 2014). "Main conclusion is that ADAMTS-12/fibulin-2 interaction potentiates anti-tumor effects in breast cancer cells." (PMID 24457941, 2014). "Immunohistochemical staining of breast cancer samples allowed the detection of both ADAMTS-12 and fibulin-2 in the connective tissue surrounding tumor area in less aggressive carcinomas." (PMID 24457941, 2014). "To determine clinical relevance of ADAMTS-12 and fibulin-2 in breast cancer, we performed an immunohistochemical analysis of a tissue array containing 16 samples of normal and breast cancer tissues." (PMID 24457941, 2014). "Overall, these results indicate that fibulin-2 and ADAMTS-12 affect ability of breast cancer cells to form mammospheres." (PMID 24457941, 2014). "Immunohistochemical detection of fibulin-2 and ADAMTS-12 was also performed using a human breast cancer tissue array." (PMID 24457941, 2014). "Interestingly, the presence and interaction of fibulin-2 and ADAMTS-12 results in anti-tumor effects in breast cancer." (PMID 38396702, 2024). "In addition, ADAMTS-12 plays a pro-tumoral role in breast cancer, by increasing the formation of subcutaneous tumors in immunodeficient SCID mice, and the capacity for migration, invasion, and mammosphere formation in breast cancer tumor cells." (PMID 33996918, 2021).
breast carcinoma (continued). "ADAMTS-12 exogenously expressed in breast cancer cells increases the formation of subcutaneous tumors in immunodeficient SCID mice, and the capacity of migration, invasion, and mammosphere formation of these cancer cells, which can be associated to a pro-tumoral effect." (PMID 33996918, 2021). "To investigate whether the presence of ADAMTS-12 could affect the behavior of breast cancer cells overexpressing ADAMTS-5, we carried out invasion assays using SK-BR-3 cells bearing in mind their endogenous expression of Fibulin-2." (PMID 28099917, 2017). "Additionally, the overexpression of ADAMTS-12 in breast carcinoma (MCF7 cell line) resulting in reduced new vessel formation exhibited an inhibitory effect in angiogenesis as well." (PMID 24876675, 2014). "However, weak or absent staining was observed in 10 out 11 (91 %) samples of grade 2 and 3 breast carcinoma for both fibulin-2 and ADAMTS-12." (PMID 24457941, 2014). "New findings have illustrated that ADAMTS-12 could elicit tumorigenesis effects when it interacts with fibulin-2 in breast cancer." (PMID 24876675, 2014). "Altogether, these data support that ADAMTS-12 fibulin-2/ interaction hampers both invasion and migration of breast cancer cells in vitro, but also that ADAMTS-12 could exert pro-tumor effects in the absence of fibulin-2." (PMID 24457941, 2014). "ADAMTS12 could promote pro-tumor properties in breast cancer cell lines." (PMID 38396702, 2024). "Consequently, the simultaneous presence of fibulin-1 and ADAMTS-1 or of fibulin-2 and ADAMTS-12 could be considered a good prognostic factor in breast cancer." (PMID 31508361, 2019). "Additionally, tumor susceptibility assays using mice lacking both Adamts12 and Fbln2 genes would be necessary to understand in depth the significance of this interaction not only in breast cancer but also in tumors from different origins." (PMID 24457941, 2014). "Therefore we examined whether ADAMTS-12 and fibulin-2 could also alter the mammosphere-forming ability of breast cancer cells." (PMID 24457941, 2014). "In this work we show that ADAMTS-12/fibulin-2 interaction induces anti-tumor effects in breast cancer cells and our data also suggest that combined detection of both proteins could be a good prognosis marker in breast cancer patients." (PMID 24457941, 2014). "The IHC score results demonstrated that ADAMTS12, AEBP1, CXCL11, and EPPK1 protein levels were higher in breast cancer samples than in normal controls." (PMID 35505821, 2022). "Two breast cancer cell lines, MCF-7 and MDA-MB-231, were employed attending to the anti-tumor role of fibulin-2 and expression profile of ADAMTS12 in this type of tumor." (PMID 24457941, 2014). "Kaplan-Meier curves revealed that a combined high expression of both ADAMTS12 and FBLN2 correlated with the best prognosis in breast cancer patients (Hts+Hfb) when compared to patients expressing low levels of both genes (Lts+Lfb) (p < 0.001)." (PMID 24457941, 2014). "The interaction of ADAMTS-12 with fibulin-2 results in a blockade of the proteolytic degradation of fibulin-2 by ADAMTS4 and ADAMTS-5 and therefore, inhibition of the tumoral properties of breast cancer cells." (PMID 33996918, 2021). "Interestingly, the degradation of fibulin-2 by either ADAMTS-4 or ADAMTS-5 is blocked by the presence of ADAMTS-12 and seems to be a target for the protective role of the fibulin-2/ADAMTS-12 interaction in breast cancer." (PMID 31508361, 2019). "Interestingly, ADAMTS-12 was found to promote tumor development in breast cancer cells lacking FBLN2 by regulating metalloproteinase." (PMID 35445008, 2022). "Further exhaustive functional and mechanistic studies will help finding out the precise role of ADAMTS-12 and fibulin-2 in relation to tumorigenesis, including the importance of the ADAMTS-12/fibulin-2 molar ratio as an indicator of potential invasiveness of breast cancer cells." (PMID 24457941, 2014).
breast carcinoma (continued). "The second relevant finding is that ADAMTS-12 could promote pro-tumor properties when is produced in breast cancer cells in the absence of fibulin-2." (PMID 24457941, 2014). "ADAMTS12 enhances tumor cell migration in PDAC, while ADAMTS15 increases cellular motility without affecting proliferation in breast cancer, paralleling the lack of a proliferative effect observed for ADAMTS13 in our study." (PMID 41211185, 2025). "In breast cancer, the interaction between the fibulin-2 and ADAMTS-12 proteins promotes antitumor effects, but the absence of fibulin-2 evokes the pro-tumor effect of ADAMTS-12 in breast cancer cells." (PMID 34063320, 2021).
colorectal cancer (13 papers, 2014 to 2025). A primary or metastatic malignant neoplasm that affects the colon or rectum. "In fact, ADAMTS-12 seems to be preferentially associated with cancer associated fibroblasts (CAFs) and immune cells (macrophages) in colorectal cancer." (PMID 33996918, 2021). "ADAMTS12 increased the transcriptional activation of β-catenin, thereby promoting cell proliferation and migration in colorectal cancer cells." (PMID 37835389, 2023). "The elevated expression of ADAMTS12 in colorectal cancer has been found to promote tumor progression through the activation of the Wnt/β-catenin pathway." (PMID 35280819, 2022). "ADAMTS12 acts as a cancer promoter in colorectal cancer via activating the Wnt/β-catenin signaling pathway in vitro." (PMID 36232317, 2022). "The participation of ADAMTS-12 with an antitumoral function has been described in colorectal carcinomas with silencing of the ADAMTS12 gene promoter by hypermethylation." (PMID 31508361, 2019). "ADAMTS-12 was found to be expressed in the fibroblasts adjacent to the tumor cells in the colorectal cancer specimens from human patients." (PMID 24876675, 2014). "The ADAMTS-12 gene promoter was hypermethylated in colorectal carcinomas and colon cancer cell lines resulting in the silence of ADAMTS-12 expression." (PMID 24876675, 2014). "Other studies support the protective role of ADAMTS-12 in colorectal cancer." (PMID 33996918, 2021). "ADAMTS12 has been identified as potential tumor suppressor in colorectal cancer." (PMID 30081852, 2018). "Therefore, ADAMTS-12 may be a promising prognostic indicator for colorectal cancer." (PMID 24876675, 2014).
lung carcinoma (13 papers, 2011 to 2025). "Ultrasound imaging highlighted tumor development on the left lung surface, and proteomic analysis identified specific biomarkers associated with lung cancer, such as ADAMTS12, BRAF, BRCA2, and TIF1α." (PMID 40584122, 2025). "Our experiments were aimed at analyzing the effects on lung tissue considering the previous inflammation phenotype and the susceptibility to lung cancer of ADAMTS-12 knock-out mice." (PMID 38396702, 2024). "Another study reported that Adamts12−/− mice exhibited a five-fold increase in the risk of developing lung cancer, demonstrating the role of ADAMTS12 as a tumor suppressor gene in lung cancer." (PMID 38808570, 2024). "After application of a urethane protocol to induce lung carcinoma, we observed that mice deficient in fibulin-2 and ADAMTS12 showed a higher incidence of lung carcinomas than their corresponding wild-type littermates." (PMID 38396702, 2024). "Mice with ADAMTS12 deletion mutations have a five-fold increased susceptibility to lung cancer, confirming the role of ADAMTS12 as a tumor suppressor gene." (PMID 36591235, 2022). "In summary, the generation of mice deficient in fibulin-2 and ADAMTS-12 contributed to the in vivo validation that the interaction between these two proteins has an antitumor role in lung cancer and has an effect in modulating the immune response after lung injury." (PMID 38396702, 2024). "In the first stage of the analysis, the mRNA expression of the ADAMTS6, ADAMTS9, and ADAMTS12 genes was assessed in lung cancer, and the obtained results were compared with data from adjacent normal tissues." (PMID 39940703, 2025). "The greatest number of differences between normal and lung cancer samples was observed for the ADAMTS12 gene (n = 110); these changes were considerably more frequent than in ADAMTS6 and ADAMTS9 (DMRs: n = 7 and n = 10, respectively)." (PMID 39940703, 2025). "A study conducted on mice showed that a deletion in the ADAMTS12 gene increases the likelihood of lung cancer by up to five times." (PMID 39940703, 2025). "We focused our studies on the double knock-out mice in a lung cancer model since the fibulin-2-/-/Adamts12-/- mice presented significant lesions in the lung parenchyma." (PMID 38396702, 2024). "Bioinformatics studies and RNA interference techniques also supported a protective role of ADAMTS-12 in lung cancer." (PMID 38396702, 2024). "In a more recent study it was indeed shown that ADAMTS12 depletion in a lung cancer cell line resulted in increased proliferation and invasion and that Adamts12-deficient mice had a 5-fold increase in lung tumor burden after urethane exposure." (PMID 34268335, 2021). "Protective role of ADAMTS-12 in lung cancer was also supported through the employment of bioinformatic approaches." (PMID 33996918, 2021). "In the urethane-induced lung cancer model, ADAMTS-12 is present in cells surrounding the highly proliferative cells within the tumor." (PMID 33996918, 2021). "Taken together our results suggest ADAMTS12 has a tumor-suppressor role in lung cancer, consistently with the results of our computational analysis." (PMID 32732999, 2020). "Specifically, our experiments reveal that lung carcinoma LL/2-luc-M38 cells display a higher proliferative and invasive potential in vitro when transfected with an ADAMTS12 shRNA." (PMID 32732999, 2020). "To validate ADAMTS12 inactivation as a driver of progression in lung carcinoma, we investigated the effect of silencing ADAMTS12 in the lung carcinoma cell line LL/2-luc-M38 using a shRNA plasmid." (PMID 32732999, 2020). "Altogether our data suggest that expression of GREM1, LOXL2, ITGA11 and ADAMTS12 by MSCs enhances primary lung cancer metastasis." (PMID 29503225, 2018). "Initial reports of ADAMTS12 being overexpressed in gastrointestinal carcinomas and a few cancer cell lines such as HeLa, A549 lung carcinoma and Burkitt’s lymphoma (Daudi) cells suggested a tumor supportive role for this metalloproteinase." (PMID 24213506, 2012).
lung carcinoma (continued). "Overexpression of ADAMTS12 in A549 lung carcinoma also resulted in the tumor growth suppression in nude mice." (PMID 24213506, 2012). "In addition, in vitro studies using M-38 lung carcinoma cells revealed an increase in their proliferative and invasive potential after being depleted of ADAMTS-12 using RNA interference techniques." (PMID 33996918, 2021). "As for lung cancer, ADAMTS12 promoted the migration and tumorigenesis." (PMID 34040054, 2021). "The four genes, GREM1, LOXL2, ADAMTS12 and ITGA11, provide a candidate stromal signature that may be functionally implicated in lung cancer dissemination." (PMID 29503225, 2018). "Additionally, subcutaneous injection of SCID mice with the highly aggressive lung carcinoma A549 cell line over-expressing ADAMTS-12 repressed tumor growth." (PMID 21494557, 2011). "Overall, the results of these studies on IL-7R, ADAMTS12, and ADRB2 indicate their anti-tumor functions in lung cancer." (PMID 38808570, 2024). "We additionally identified statistically significant mutations in the metalloproteinases ADAMTS2 (15%) and ADAMTS12 (20%), and in GAS7 (12%) and NTM (10%) (Q < 0.01, Methods section), which so far have not been reported as significantly mutated in any other lung cancer subtype." (PMID 29535388, 2018).
gastric cancer (8 papers, 2011 to 2025). A primary or metastatic malignant neoplasm involving the stomach. "Here, we embarked from the transcriptome analysis of gastric cancer based on TCGA database and clinical patients and confirmed that ADAMTS12 was significantly overexpressed in GC tissues, the up-regulated expression was associated with poor overall survival." (PMID 34040054, 2021). "To investigate the effect of ADAMTS12 on cell proliferation in vitro, we transfected specific ADAMTS12 siRNA into a gastric cancer cell line (MKN45)." (PMID 34040054, 2021). "ADAMTS12 is highly expressed in tumor tissues, and its elevated expression was correlated with a poor prognosis in multiple cancer types, such as pancreatic ductal adenocarcinoma, head and neck cancers, and colorectal and gastric cancers." (PMID 37835389, 2023). "Then we detected the expression of ADAMTS12 in human gastric cancer cell lines (MKN45), it was highly expressed and could be used for further investigation." (PMID 34040054, 2021).